ASAP1 (ArfGAP with SH3 domain, ankyrin repeat and PH domain 1)
Diseases named in the same sentence as ASAP1 in open-access papers (continued):
Sharing a sentence is not in itself a finding about the gene and the disease.
tumor (continued). "The established mouse xenograft model was injected with wildtype (WT) (blue) or ASAP1+/− SGC-7901 cells (red), and then tumor growth was monitored." (PMID 36792578, 2023). "ASAP1 is an ADP-ribosylation factor GTPase-activating protein, which is involved in tumor metastasis." (PMID 32541093, 2020). "Circ-ASAP1 was reported to facilitate HCC cell proliferating and invading processes by regulating miR-326/miR-532-5p-MAPK1 signaling and mediate tumor-related-macrophage infiltrating process through the control over the miR-326/miR-532-5p-CSF-1 path." (PMID 32665846, 2020). "We performed immunostaining of EGFR, ASAP1, ERBB2, ERBB4 and β-catenin in HBL tumor tissue from an expanded cohort of children treated with liver transplantation (n = 19) or with surgical resection (n = 40) and biopsy (n = 1)." (PMID 27910913, 2016). "Given the elevated expression of ASAP1 in PTC, we hypothesized that ASAP1 promotes tumor progression in PTC cells." (PMID 40742091, 2025). "Indeed, chromosome 3 contains the tumor suppressor gene, BAP1; while in the 8q region, we can find tumor-promoting genes, including MYC (8q24) and ASAP1 (DDEF1; 8q24)." (PMID 31277366, 2019). "We therefore evaluated whether EGFR, ASAP1, ERBB2 and ERBB4, which signal downstream after ligation of EGF, and which show aberrant expression in several other invasive cancers, would also predict HBL tumor invasiveness." (PMID 27910913, 2016). "We found that when the Oxa was 5 mg/kg/day, ASAP1+/− SGC-7901 tumor volume was significantly smaller than that in the saline group, while SGC-7901 WT tumor volume was not significantly different from that of the saline group." (PMID 36792578, 2023). "When examining separately each tumor site subgroup, we strikingly observed that the correlations between SRC expression and the SRC-related proteins FAK, ASAP1, and HERG1 were specific to the larynx and not the pharynx." (PMID 31731442, 2019).
infection (3 papers, 2015 to 2020). The state of being infected such as from the introduction of a foreign agent such as serum, vaccine, antigenic substance or organism. "Preliminary experimental results showed that Asap1 knockdown enhanced Mm infection efficiency by ~2-fold, but a single knockdown of Asap1a or Asap1b did not cause increased susceptibility to Mm over controls." (PMID 33194781, 2020). "In this study, we explored the role of ASAP1 in macrophage migration during Mtb infection, taking advantage of the optical transparency of the zebrafish larvae infection model." (PMID 33194781, 2020). "Despite the need for further elucidation of mechanisms and infection processes, our zebrafish model highlights the importance of ASAP1 in host resistance to mycobacterial entry." (PMID 33194781, 2020). "In particular, we explored the function of Asap1 in the process of zebrafish infection with Mm within the first 10 days of development, when host and pathogen interact in the sole context of innate immunity in vivo." (PMID 33194781, 2020). "To dissect the mechanism of Asap1 in regulating zebrafish against infection, we further examined the effect of Asap1 on macrophage migration in zebrafish by tailfin click and Mm hindbrain injection." (PMID 33194781, 2020). "Nevertheless, the detailed regulatory effects of ASAP1 during host infection with Mycobacterium remain to be elucidated." (PMID 33194781, 2020). "To determine the influence of ACAP1, ADAP1, and ASAP1 on Salmonella remodeling of the cytoskeleton, we examined Salmonella invasion after a 15-min infection of Caco cells individually expressing recombinant hemagglutinin (HA)-tagged Arf GAPs." (PMID 25670778, 2015). "Considering a further finding that ArfGEFs and ArfGAPs might collaborate to control pathogen infection, we speculate that ASAP1-mediated regulation of mycobacterial invasion occurs through various temporally and spatially adjusted mechanisms." (PMID 33194781, 2020). "These Asap1-depleted zebrafish also exhibited decreased macrophage migration in response to tail injury or upon infection with M. marinum in the hindbrain ventricle, which was also proved in THP1-derived macrophages of knockdown ASAP1." (PMID 33194781, 2020). "Curtis and colleagues have not detected ASAP1 expression among lymphocytes and monocytes after the infection of Mycobacterium bovis BCG, except DCs." (PMID 31089398, 2019). "This outcome suggests that Asap1-induced elevation in bacterial load might not strongly influence infection lethality initiated via normal Mm inocula, at least in the zebrafish model." (PMID 33194781, 2020).
kidney diseases (1 paper, 2024). "Among them, Daam2, Pdlim2, Asap1, and Sphk2 all of which have a known relationship to kidney diseases." (PMID 39278930, 2024).
ASAP1 also shares sentences with these, for which no sentence is quoted: triple-negative breast carcinoma (3 papers); colorectal adenocarcinoma (2); bladder neoplasms (1); brucellosis (1); carcinoma in situ (1); clear cell renal cell carcinoma (1); female infertility (1); Holt-Oram syndrome (1); infectious disease (1); inflammatory bowel disease (1); invasive ductal carcinoma (1); leukemia (1); liver disease (1); lymph node metastasis (1); neurodegenerative disease (1); pancreatic ductal adenocarcinoma (1); Papillary Thyroid Cancer (1); renal carcinoma (1); Type 1 Diabetes (1); type 2 diabetes mellitus (1).